ENSG00000251744
Gene: Small nucleolar RNA gene on chromosome 8 (139,108,430 to 139,108,534, forward strand). Ensembl gene ENSG00000251744.
Homologues: Paralogues in human: SNORA25 (73% identical), SNORA25B (71% identical).